FANCD2 (FA complementation group D2)
Description:
Required for maintenance of chromosomal stability. Promotes accurate and efficient pairing of homologs during meiosis. Involved in the repair of DNA double-strand breaks, both by homologous recombination and single-strand annealing. The FANCI-FANCD2 complex binds and scans double-stranded DNA (dsDNA) for DNA damage; this complex stalls at DNA junctions between double-stranded DNA and single-stranded DNA (By similarity). May participate in S phase and G2 phase checkpoint activation upon DNA damage. Plays a role in preventing breakage and loss of missegregating chromatin at the end of cell division, particularly after replication stress. Required for the targeting, or stabilization, of BLM to non-centromeric abnormal structures induced by replicative stress. Promotes BRCA2/FANCD1 loading onto damaged chromatin. May also be involved in B-cell immunoglobulin isotype switching.
Synonyms: FACD; FAD; FA-D2; FA4; FAD2; FANCD
Tractability: Small molecule: a structure with a bound ligand is known. PROTAC: UniProt records ubiquitination sites on it; ubiquitination databases record sites on it.
Target class: Other nuclear protein
Gene: Protein-coding gene on chromosome 3 (10,026,370 to 10,101,937, forward strand). Ensembl gene ENSG00000144554.
Subcellular location: Nucleus
Subcellular location (Human Protein Atlas): Nuclear bodies; Nucleoplasm; Cytosol; Nucleoli
Pathways (Reactome):
DNA Repair: Fanconi Anemia Pathway
Gene Ontology:
Molecular function: DNA polymerase binding; protein binding
Biological process: response to gamma radiation; interstrand cross-link repair; mitotic intra-S DNA damage checkpoint signaling; DNA repair
Cellular component: DNA repair complex; nuclear body; nucleolus; nucleoplasm; nucleus; chromatin; condensed chromosome
Genetic constraint (gnomAD): Loss-of-function variants: 91 observed, 139.49 expected, observed/expected ratio (o/e) 0.65, 90% interval 0.55 to 0.78. The upper end of that interval is the gene's LOEUF score, 0.78, which puts it in group 3 of 6, group 1 being the genes least tolerant of losing a copy. Missense variants: 1,276 observed, 1,460.7 expected, observed/expected ratio (o/e) 0.87, 90% interval 0.83 to 0.92. Synonymous variants: 456 observed, 530.57 expected, observed/expected ratio (o/e) 0.86, 90% interval 0.8 to 0.93.
Gene-disease validity (ClinGen):
ClinGen rates the evidence that FANCD2 causes each of these diseases.
Fanconi anemia complementation group D2 (autosomal recessive): Definitive. Fanconi anemia caused by mutations of the FANCD2 gene.
Cancer hallmarks: tumour promoting inflammation (suppresses); genome instability and mutations (suppresses); suppression of growth (promotes); escaping programmed cell death (promotes); invasion and metastasis (suppresses)
Homologues: Orthologues: macaque FANCD2 (96% identical), chimpanzee FANCD2 (93% identical), dog FANCD2 (86% identical), pig FANCD2 (85% identical), guinea pig FANCD2 (77% identical), rat Fancd2 (76% identical), mouse Fancd2 (75% identical), tropical clawed frog fancd2 (58% identical), zebrafish fancd2 (53% identical), Drosophila melanogaster Fancd2 (24% identical), Caenorhabditis elegans fcd-2 (18% identical).
Diseases named in the same sentence as FANCD2 in open-access papers:
FANCD2 is named in the same sentence as 176 diseases in open-access papers, as found by Europe PMC text mining. Sharing a sentence is not in itself a finding about the gene and the disease. The quoted sentences say what the papers report.
Fanconi anemia (260 papers, 2008 to 2026). Fanconi anemia (FA) is a hereditary DNA repair disorder characterized by progressive pancytopenia with bone marrow failure, variable congenital malformations and predisposition to develop hematological or solid tumors. "FANCA is the most frequently mutated gene in Fanconi Anemia, encoding a protein that forms part of the FA core complex responsible for mediating FANCD2 ubiquitylation during ICL repair." (PMID 40630542, 2025). "What is already known is that the variant is located in the region of specific menin interaction with FANCD2 (UniProt), in turn a protein encoded by a gene involved in DNA repair and mutated in patients with an inherited cancer-prone syndrome, Fanconi anemia." (PMID 38294658, 2024). "To date, only one case of this specific mutation in the FANCD2 gene has been documented in a patient with Fanconi anemia." (PMID 39768544, 2024). "Previous studies have demonstrated that a functional Fanconi anemia (FA) pathway prevents the unscheduled accumulation of transcription-associated R-loops, with FANCD2 monoubiquitination playing a critical role." (PMID 38488661, 2024). "Fancd2 was initially found to be an essential protein for the development of Fanconi anemia, but subsequent studies have revealed its association with cancer development." (PMID 38218826, 2024). "The protein encoded by FAAP100 regulates FANCD2 monoubiquitination and the stability of the Fanconi anemia core complex, playing a role in the Fanconi anemia-associated DNA damage response." (PMID 37372448, 2023). "This was unexpected, because patients with a FANCD2 mutation are diagnosed with Fanconi anemia (FA), a bone marrow failure syndrome caused by defective DNA repair, rather than telomere dysfunction." (PMID 37834388, 2023). "FANCD2 is implicated in the Fanconi anemia pathway, to orchestrate the maintenance of genome integrity and prevention from diseases including cancer." (PMID 36832225, 2023). "FAAP20 is a Fanconi anemia (FA) protein that associates with the FA core complex to promote FANCD2/FANCI monoubiquitination and activate the damage response to interstrand crosslink damage." (PMID 37620397, 2023). "Fanconi Anemia patients with pathogenic variants in the FANCD2 are at high risk of developing ESCC, probably due to the role of this gene in accelerating cell cycle progression." (PMID 35326673, 2022). "Studies have shown that FANCD2 re-expression was associated with glioma grade and chemical inhibition of the Fanconi Anaemia pathway sensitises gliomas to chemotherapeutic agents." (PMID 34689169, 2021). "In FL, the most frequently mutated DNA repair pathway (21 variants in 12 cases) was Fanconi anemia (FA), in particular in the gene FANCD2 with even several mutations in the same patient." (PMID 34884820, 2021). "Many studies have shown that mutations and abnormal expression of the FANCD1 and FANCD2, two major genes in the Fanconi anemia pathway, are significantly associated with poor prognosis of CCA." (PMID 33472169, 2021). "In the linear regression analysis for CSAs, two associations included a Fanconi anemia gene FANCD2 (Fanconi anemia complementation group D2) and an intronic variant for mismatch repair (MMR) pathway gene PMS2 (PMS1 homolog 2, mismatch repair system component)." (PMID 34220964, 2021). "Fanconi anemia complementation group D2 (FANCD2) encodes a protein required for the Fanconi anemia (FA) pathway, which is mono-ubiquitinated in response to DNA damage and essential for repairing DNA inter-strand crosslinks (ICLs)." (PMID 32906798, 2020). "In the Fanconi anemia complementation group A (Fanca) and Fanconi anemia complementation group G (Fancg) deficient mice, whose Fancd2 activation and FA/Brca1 pathway functionality are abolished, the neuron number is reduced at the dorsal telencephalon 32,49." (PMID 33029090, 2020).
Fanconi anemia (continued). "Altogether, these results suggest that there is an increase in R-loop formation in RNF2 KO cells, and the Fanconi Anemia proteins FANCD2 and FANCI are necessary to prevent the R-loop-associated genomic instability in RNF2 KO cells." (PMID 32142505, 2020). "In the rare genetic disease Fanconi anaemia (FA), the loss of FANCD2 activity has been shown to contribute to an accumulation of genetic mutations and therefore promote leukaemogenesis or tumorigenesis." (PMID 32372224, 2020). "FANCD2 is the key activated target of the FA pathway, deficient in Fanconi Anemia chromosomal instability and cancer-prone disorder, and is involved in replication stress response and inter-strand crosslink (ICL) repair." (PMID 31320994, 2019). "As increased activities of the Fanconi Anemia pathway is associated with a subpopulation of OVCAs65, the increased FANCD2 expression by FAC is a notable observation." (PMID 31434871, 2019). "Fanconi anemia complementation group D2, FANCD2 variants p.N545S and p.R174Q were present in separate samples, the latter variant having predicted effects on protein function (Polyphen score .96), but also having low sequence depth." (PMID 31346352, 2019). "FANCD2 accumulation is associated with HPV-activated Fanconi anemia pathway and is essential for the maintenance of viral episomes in HPV-infected cells." (PMID 31775835, 2019). "Loss of Fancd2 leads to replication stress intolerance and Fanconi Anemia, where haematopoietic stem cell (HSC) function is compromised." (PMID 30254368, 2018). "FANCD2, when mutated, is one of the causative genes of Fanconi anemia, an inherited disorder characterized by developmental defects, progressive bone marrow failure, and predisposition to cancer." (PMID 30087422, 2018). "The only exception is the variant in FANCD2 (c.2613A > C / p.K871N) which is in ClinVar associated with Fanconi anemia." (PMID 29515789, 2018). "A splice site mutation (c.2715 + 1G > A, E906LfsX4, rs201811817) in the Fanconi anemia (FA) gene, FANCD2, showed enrichment in the Northern Finnish hereditary cohort (3/247, 1.2%) when compared to controls (p = 0.036, OR = 7.5 and 95% CI = 1.3–45.3)." (PMID 28386063, 2017). "A deleterious c.2715 + 1G > A mutation in the Fanconi anemia gene, FANCD2, was over two times more common in the combined Finnish hereditary cohort compared to controls." (PMID 28386063, 2017). "Exposure of H1299 cells to AITC for 6 hours induced a robust increase in γH2AX (phosphorylated form of histone 2 variant X at Serine 139) foci and FANCD2 (Fanconi anemia, complementation group D2) foci compared to DMSO treated cells." (PMID 25742788, 2015). "FANCD2 is a product of one of the genes associated with Fanconi anemia (FA), a rare recessive disease characterized by bone marrow failure, skeletal malformations, developmental defects, and cancer predisposition." (PMID 25489943, 2014). "This is also coincided with the diminished levels of excision repair protein (XRCC1), replication checkpoint kinase protein 1 (Chk1) and other replication stress associated Fanconi anemia (FA)-BRCA gene products FANCD2 and FANCJ." (PMID 25216266, 2014). "Additionally, FANCD2 deletions are implicated in Fanconi anaemia, a genetic disease characterised by chromosomal instability and defective DNA repair." (PMID 40320296, 2025). "These genes are linked with a range of X-linked and autosomal disorders, e.g., TMLHE (X-linked Autism), CDKL5 (Developmental Encephalopathy), FANCD2 (Fanconi anaemia), FLT4 (congenital heart defects), FTCD (Glutamate formiminotransferase deficiency), and DOCK8 (DOCK8 immunodeficiency syndrome)." (PMID 38033082, 2023). "The known functions of these genes cluster into two main functional families, 3 out of 8 are DNA repair genes associated with Fanconi anemia: FANCD2, SLX4, and FANCA, while 3 out the 8 are HLA genes comprising the major histocompatibility complex (MHC) involving immunity." (PMID 35962345, 2022).
Fanconi anemia (continued). "Moreover, since monoubiquitination occurs on the evolutionarily conserved lysine residues, variants affecting FANCD2 at K561 residue seem to result in major molecular defects in response to DNA damage agents in the Fanconi Anemia cells." (PMID 36011265, 2022). "FANCD2 gene mutation is believed to be one of the causative mutations in Fanconi anemia, and despite many case reports that link the FANC gene mutation to multiple congenital anomalies and disease, there is no case report found to link it with genitalia abnormalities." (PMID 34327028, 2021). "Fanconi anemia patients with germline genetic defects in FANCD2 are highly susceptible to cancers." (PMID 32906798, 2020). "Fanconi anemia patients with germline FANCD2 defects are susceptible to cancers." (PMID 32906798, 2020). "Similarly, up-regulation of FANCD2, which encodes a key member of the Fanconi anemia and breast cancer pathway of DNA repair, was associated with poor outcome of patients with MM, particularly those with high-risk disease." (PMID 25838973, 2015). "Fanconi Anemia associated Protein phosphorylation is down modulated by leukaemogenic PTKs, this protein can regulate Fanconi protein repair complex specifically via FANCD2 ubiquitination." (PMID 22745689, 2012). "In addition, pachytene-like UBR2−/− spermatocytes showed a normal staining pattern for FANCD2, a component of the Fanconi anemia (FA) complex, whose monoubiquitylation is a hallmark for recruitment of FA components and other repair proteins." (PMID 22616001, 2012). "It is interesting that most of the Fanconi anaemia genes encode proteins that form a nuclear core complex with a function of monoubiquitination of FANCD2, but FANCD1 (BRCA2) and BRIP1/FANCJ function downstream of this and they both have a more defined role in DNA damage repair." (PMID 19127258, 2009). "In a model of alcohol-mediated DNA damage, β2SP is critical for maintenance of genomic stability by supporting DNA repair through β2SP-dependent activation of Fanconi anemia complementation group D2 (Fancd2), a core component of the Fanconi anemia complex." (PMID 41109667, 2026). "The actions of UL138 are due, in part, to its modulation of pathways regulated by the cellular deubiquitinating complex that targets proliferating cell nuclear antigen (PCNA) and Fanconi Anemia effectors, FANCD2 and FANCI." (PMID 41533576, 2026). "Firstly, 2 of the 3 tumors with elevated signature 3 each had 2 pathogenic germline variants both in HR and Fanconi anemia genes (BRCA2/FANCE, BRCA2/FANCD2)." (PMID 40072012, 2025). "The FANCD2 (Fanconi Anemia Complementation Group D2) gene is involved in the regulation of ferroptosis and DNA repair, through the activation of cell cycle checkpoints following DNA damage." (PMID 40415137, 2025). "Collectively, these findings demonstrate that FANCD2 responds to not only DNA damage but also OA exposure, providing insights into the pathogenesis of lipid dysregulation in Fanconi anemia." (PMID 41065314, 2025). "FANCD2, a key protein in the Fanconi anemia (FA) pathway, participates in DNA damage repair, cell cycle regulation, apoptosis, and chromatin remodeling, playing an important role in cancer via phosphorylation or ubiquitination." (PMID 40356980, 2025). "In the DNA damage response, FANCD2 requires the Fanconi anemia core complex to regulate downstream DNA repair process." (PMID 41065314, 2025). "FANCD2, a crucial protein in the Fanconi anemia/BRCA pathway, is one of these and has a complex relationship with OC." (PMID 41405958, 2025). "While Fanconi Anemia-associated genes BRCA2, FANCA and PALB2 are known PCa GT candidates, FANCD2 outranked FANCA, with FANCG, ECCR4, FANCE and FANCI (in order of ranking) potential candidates." (PMID 41038821, 2025). "FANCD2 is a key factor in the Fanconi anemia pathway, and its function depends on the activation of Ataxia telangiectasia mutated (ATM)/Chk2 signaling." (PMID 40725100, 2025).
Fanconi anemia (continued). "The diagnosis of Fanconi anemia was confirmed by FANCA gene mutation in 10 patients and FANCD2 mutation in one." (PMID 39941721, 2025). "The formation of R-loops promotes the accumulation of Fanconi anemia factors (FANCD2, FANCA, FANCM, and BRCA2) at fragile sites, and the DEAD-box RNA helicase DDX47 is recruited to interact with FANCD2 to resolve the R-loops." (PMID 40271193, 2025). "In response to DNA interstrand crosslinks, eight Fanconi anemia proteins assemble into a nuclear E3 ubiquitin ligase complex, which mono-ubiquitinates FANCD2 and FANCI." (PMID 38323120, 2024). "FANCD2 is a key protein in Fanconi anemia signal pathway and plays an important role in many aspects of cell life, especially in DNA damage response." (PMID 38509102, 2024). "Fanconi anemia complementation group D2 (Fancd2) is a nuclear protein involved in DNA damage repair." (PMID 38218826, 2024). "In cells expressing the p.L605F isoform, there was a significant reduction in the localization of FANCD2, a component of the FANCI-FANCD2 (ID2) binding complex in the Fanconi anemia (FA) pathway, to sites of induced DNA damage." (PMID 39767562, 2024). "Fanconi anemia complementation group D2 (Fancd2) has been shown to be closely related to drug resistance in cancer cells." (PMID 38218826, 2024). "FANCD2 is a member of the Fanconi anemia pathway genes involved in DNA repair and genomic stability." (PMID 39051418, 2024). "USP1 deubiquitinates mono-ubiquitinated FANCD2/I, thereby reversing the critical step in the activation of the Fanconi anemia pathway." (PMID 38323120, 2024). "This protein is a DNA-binding protein from the Fanconi anemia group D2, or FANCD2, under the same umbrella of over 22 FANC proteins." (PMID 38254661, 2024). "FANCD2 is a member of the Fanconi anemia pathway genes involved in DNA repair and genomic stability, and aberrations of this gene are associated with many cancers." (PMID 39051418, 2024). "Enrichment analysis further highlights the potential impact of FANCD2 on Fanconi anemia (FA) pathway and cell cycle regulation." (PMID 38443946, 2024). "The homozygous Fanconi anaemia complementation group D2 knock-out mice (Fancd2−/−) develop multiple ovarian tumour phenotypes in a sequential manner as they age." (PMID 37174061, 2023). "UHRF1 accumulation at damage sites precedes the recruitment of important effector proteins, such as FANCD2 (Fanconi anemia complementation group D2), which, in turn, is necessary for the recruitment of other factors of the Fanconi anemia (FA) repair pathway." (PMID 37630248, 2023). "In our experiments, the most significant upregulated genes included FANCD2, a player in Fanconi anemia (FA), and several genes playing a role in the HR-mediated repair of double-strand breaks (DSBs) such as BARD1, BRCA2, RAD51 and DNA2." (PMID 36672885, 2023). "FANCD2 is a component of the Fanconi anaemia (FA) complex, which is known to promote the loading of the ERCC1/XPF complex at ICLs." (PMID 37226898, 2023). "USP1 targets FANCD2/FANCI to regulate the Fanconi anemia pathway (FA) and, together with USP7, targets translesional DNA repair (TLS)." (PMID 37892185, 2023). "This suggested that the Fanconi Anemia pathway plays a role in TE repression in early PGCs, likely through a mechanism involving the promotion of repressive H2A/H4R3me2s marks on TEs by FANCD2 and the acceleration of this process by Prmt5." (PMID 37566603, 2023). "Fanconi anemia complementation group D2 (FANCD2) belongs to one of the DNA repair markers, which is a class of Fanconi anemia (FA) proteins that regulate DNA damage responses and maintain genomic integrity." (PMID 36246623, 2022). "FANCD2 is a component of the Fanconi anemia (FA) DNA repair pathway, and its nuclease activity has been shown to have a protective role against expansion in an HD cell model." (PMID 36292679, 2022). "FANCD2 is a gene involved in cell cycle regulation and in Fanconi Anemia, a genomic instability disorder." (PMID 35326673, 2022).